LINC02474 (long independently transcribed non-coding RNA 2474)
Synonyms: RP11-400N13.2; lncSLCC1
Gene: Long non-coding RNA gene on chromosome 1 (221,966,341 to 221,984,964, forward strand). Ensembl gene ENSG00000228437.
Diseases named in the same sentence as LINC02474 in open-access papers:
LINC02474 is named in the same sentence as 5 diseases in open-access papers, as found by Europe PMC text mining. Sharing a sentence is not in itself a finding about the gene and the disease. The quoted sentences say what the papers report.
colorectal cancer (2 papers, 2023 to 2025). A primary or metastatic malignant neoplasm that affects the colon or rectum. "The down-regulation of LINC02474 promoted the expression of GZMB, and the interference of GZMB could increase the metastatic abilities of colorectal cancer cells while reducing apoptosis." (PMID 37770840, 2023).
colon cancer (1 paper, 2022). "A total of 709 autophagy-related genes were identified in colon cancer tissues, and 11 autophagy-related lncRNAs (AL138756.1, LINC01063, CD27-AS1, LINC00957, EIF3J-DT, LINC02474, SNHG16, AC105219.1, AC068580.3, LINC02381, and LINC01011) were finally selected and set as prognosis-related lncRNAs." (PMID 36035142, 2022).
rectal cancer (1 paper, 2026). A primary or metastatic malignant neoplasm that affects the rectum. "The LINC02474 oncogene prevents apoptosis and promotes metastasis in CRC by inhibiting GZMB expression, a process that is associated with the poor prognosis of rectal cancer patients (39, –, 42)." (PMID 41358726, 2026).
tumor (3 papers, 2021). "Altogether, the results suggested that LINC02474 was an oncogenic lncRNA, and promoted tumor metastasis both in vivo and in vitro but inhibited CRC cells’ apoptosis." (PMID 33898319, 2021).
cancer (2 papers, 2021 to 2022). A tumor composed of atypical neoplastic, often pleomorphic cells that invade other tissues. "Among the 11 autophagy-related lncRNAs, 8 lncRNAs were already verified to be associated with cancer development: LINC01063, CD27-AS1, LINC00957, EIF3J-DT, LINC02474, SNHG16, LINC02381, and LINC01011." (PMID 36035142, 2022). "Subsequently, RNA-seq data showed that depletion of LINC02474 might affect the expressions of cancer-related genes, such as GZMB." (PMID 33898319, 2021).